IL10 (interleukin 10)
Diseases named in the same sentence as IL10 in open-access papers (continued):
Sharing a sentence is not in itself a finding about the gene and the disease.
COVID-19 (continued). "Similarly, considering mortality, a total of 10 studies were used for pairwise comparison between survivor and non-survivor COVID-19 cases for IL-10, with a total of 2810 subjects in the survivor group vs. 569 in the non-survivor group." (PMID 35572964, 2022). "The elevated IL-10 levels in NK cells as well as CD4+ and CD8+ T cells of severe patients might be also considered as a protective response against the harmful effect of cytokine storm seen in COVID-19." (PMID 36110850, 2022). "Furthermore, it determined four possible therapeutic targets that increase the Th1 compartment in severe COVID-19: the activation of the IFN-γ pathway, or the inhibition of TGF-β or IL-10 pathways or SOCS1 protein; from these, inhibiting SOCS1 has the lowest number of predicted collateral effects." (PMID 36678366, 2022). "High levels of IL-6, IL-10, monocyte chemoattractant protein (MCP)-1, macrophage inflammatory protein (MIP)-1α and MIP-1β are detected in bronchoalveolar lavage fluid (BALF) of COVID-19 patients, indicating inflammatory environment with high monocyte chemoattractants." (PMID 35589689, 2022). "In addition, studies report elevated levels of IL-10 in severe and non-survivor cases relative to mild or survivor COVID-19 cases." (PMID 35572964, 2022). "It was found a significant decrease in the IL-12p70/IL-10 ratio between the control group without SIgA and the control group with SIgA, as well as in the IFN-γ/IL-10 ratio between the control group without SIgA, the control group with SIgA, and the COVID-19 group with SIgA." (PMID 35686128, 2022). "Data collected revealed that circulating NKT from COVID-19 patients produced significantly less IFN-γ but more IL-17 compared with cells from healthy donors even if these cytokines were more represented in ETAs than plasma, and decreased the production of IL-12A and IL-10 compared to control." (PMID 35159352, 2022). "In the current study, any genotype associated with IL6 rs1800796, IL-10 rs1800896, TNF -α rs1800629, and IFITM3 rs12252 SNPs was significantly different between COVID-19 survivors with and without post-COVID pain, and, therefore, also with different pain phenotype features." (PMID 36233516, 2022). "Furthermore, a clear clustering of cytokines (IL-6, TNF-α, IFN-γ, IFN-α, SDF-1α, MIP-1α, MIP-1β, G-CSF, IL-10, CX3CL1 and IL-4) was observed in a PCA for critically ill COVID-19 patients during the first wave who presented a bacterial superinfection during their stay at the ICU." (PMID 35007290, 2022). "In this regard, Gal-1 appears to be involved in the COVID-19 pathogenesis, finding a correlation between its blood level, proinflammatory cytokines, and clinical parameters (chest radiography, dry cough); elevated serum Gal-1 values were correlated with IL-1β, IL6, IL-10, IL-23, and IL-33." (PMID 35897786, 2022). "In addition to these findings, it was observed in the intergroup analysis that the COVID-19 group without SIgA showed higher levels of IL-10, IL-13, and IL-17A than the control group without SIgA." (PMID 35686128, 2022). "Limiting CRS is especially important for COVID-19 patients, who often display a cytokine storm even in the absence of such therapies, with increased levels of inflammatory cytokines and chemokines (TNF-α, IL-1, IL-6, IL-8, IL-10, IL-18, and MCP-1) that severely damage pulmonary tissue." (PMID 35546150, 2022). "Elevation of IL-10 levels in NK cells and reduction of CD3+ and CD8+ T cells in severe patients might be considered as a protective response against the harmful effect of cytokine storm seen in COVID-19." (PMID 36110850, 2022). "The second phase, which is much more crucial in COVID-19 because it is an intracellular viral infection, results in the secretion of a variety of cytokines into the bloodstream by T cells and macrophages, of which IL1-β, IL-2, IL-8, IL-10, IL-6, IL-12, IFN-γ, and TNF-α are the best known." (PMID 35874678, 2022).
COVID-19 (continued). "Anti-inflammatory cytokines, such as IL-10, showed a downward trend in unvaccinated patients with COVID-19, compared with those in patients with COVID-19 who had been vaccinated; however, the difference was not statistically significant (5.15 [3.93–6.34) pg/mL vs. 5.80 [4.20–7.20] pg/mL, P = 0.345)." (PMID 35984113, 2022). "In particular, mild COVID-19 is characterized by increase of IFN-α, IFN-γ, IL6, IL10, IL1RA [TE87, TE88, TE89], while severe disease is characterized by a downregulation of IFNα, and a parallel up-regulation of IFN-β, IFN-γ, IL6, TNF, IL10, CCL7 [TE89, TE90, TE94]." (PMID 34876157, 2021). "COVID-19 relevant inflammatory cytokines like interleukin (IL)-6, IL-8, tumor necrosis factor-α (TNF-α), monocyte chemoattractant protein-1 (MCP-1) or IL-1β, and anti-inflammatory cytokines like IL-10 or IL-1 receptor antagonist (IL-1ra) were shown to correlate with disease severity." (PMID 34177967, 2021). "Nevertheless, it is not clear if overactivation or suppression of IL-10 could improve clinical severe manifestations of COVID-19; more knowledge related to this topic is needed." (PMID 34829906, 2021). "Neither immunosuppressive drugs potentially present in the plasma of COVID-19 patients nor IL-10 or degradation of L-tryptophan could explain the inhibitory effects of COVID-19 plasma." (PMID 34021143, 2021). "Notably, IP-10, together with IL-6 and IL-10, is reported to constitute a severity-related triad that anticipates subsequent clinical progression (specifically) in COVID-19 patients, but not in non-COVID-19 patients with lower respiratory tract infections." (PMID 33673459, 2021). "Particularly, the CRS-related cytokines, including IL-6, IL-1β, IL-10, IL-18, and IFN-γ, displayed progressive increase along disease severity from healthy controls to mild and severe patients, highlighting the broad and strong inflammatory responses in severe COVID-19 patients." (PMID 33712622, 2021). "Our study suggests that seven indices (T, Th, Tc, IL-6, IL-10, RBC, Hb) are helpful for early diagnosis of COVID-19 severity in children, and may provide a laboratory basis for clinicians to offer timely treatment to children with critical COVID-19." (PMID 33865340, 2021). "While the role for these cells during COVID-19 has not been fully explored, they may contribute to dysregulated immunity, IL-10 production, or other deleterious tissue responses." (PMID 34185704, 2021). "Similarly, we did not observe differences in IL-10 levels between critical and mild COVID-19 patients." (PMID 34276659, 2021). "When we performed unbiased K-means clustering of the protein analyzed, we found that COVID-19 patients were significantly enriched in cluster 3, which is characterized by a unique signature of IFNs (which encompasses all three IFN families) and IL-10 production (STAR Methods)." (PMID 34492226, 2021). "Moreover, the serum levels of IFN-γ, TNF-α, IL-2, IL-4 and IL-10 were not correlated with disease severity among COVID-19 patients." (PMID 34123873, 2021). "A significant increasing trend of IL-1β, IL-1ra, IL-2, IL-4, IL-5, IL-6, IL-7, IL-8, IL-10, IL-12(p70), IL-15, IL-17, FGF-b, G-CSF, GM-CSF, IFN-γ, IP-10, MCP-1, MIP-1α, PDGF, TNF-α, and VEGF was observed in the three groups (Controls ≤ Mild COVID-19 ≤ Severe COVID-19)." (PMID 34675240, 2021). "From the results of COVID-19 clinical research, we can find CPMs can regulate the proportion of lymphocyte and leukocyte, significantly reduce the level of inflammation factors such as CRP, D-dimer, PCT, IL6, IL10, IL17, TNF-α, and IFN-γ, and increase the level of IL4." (PMID 34335247, 2021). "Interestingly, IL-10 was higher on average in COVID-19-positive than in COVID-19-negative patients (32.7 (21.4–61.5) versus 12.7 (5.9–28.5))." (PMID 34960751, 2021).
COVID-19 (continued). "Additionally, in non-severe COVID-19—although significantly lower than severe ones—blood-cytokine levels (for example IL-1β, IL-1RA, IL-2R, IL-6, IL-7, IL-8, IL-9, IL-10, IFN-γ, TNF-α, G-CSF, GM-CSF, IP10, MCP1), can be increased." (PMID 34572585, 2021). "The results showed that there were significant differences in the levels of IL-2, IL-10, absolute count of lymphocyte subsets (CD3+ T cells, CD3+CD4+ T cells, CD3+CD8+ T cells, and CD19+ B cells), CD16+CD56+ NK cells, and neutrophils between patents with COVID-19 and cancers." (PMID 34712741, 2021). "Another complementary study has not only confirmed that severe COVID-19 patients display significantly higher plasma levels of IL-6, IL-10, and TNF-α than mild cases but also demonstrated a negative correlation between the plasma concentration of these cytokines and the recovery phase." (PMID 34209845, 2021). "In lungs, similar phenomenon is observed as infection with COVID-19 initiates alveolar injury, resulting in inflammatory response that includes production of inflammatory cytokines (such as IL-1β, IL-2, IL-6, IL-8, TNF-α and IL-10), which lead to more injury to tissues and the capillary endothelium." (PMID 33679215, 2021). "COVID-19 patients displayed similar T-cell exhaustion to non-COVID-19 patients, but with a more unbalanced inflammatory/anti-inflammatory cytokine response (IL-6/IL-10 and TNF-α/IL-10 ratios)." (PMID 33272291, 2020). "The IL-6/IL-10 ratio may also be an important indicator for assessing the immune status of COVID-19 patients, although no established cutoff value is available to identify SIRS and/or MARS." (PMID 33240265, 2020). "Patients with COVID-19 had high amounts of IL-1β, IFN-γ, IP-10, and MCP-1, indicating an activated Th1 response; besides, SARS-CoV-2 could also initiate increased secretion of Th2 cytokines, especially IL-10, which is different from SARS-CoV infection." (PMID 32426374, 2020). "Another study showed a similar trend, with plasma concentrations of IL-2, IL-7, IL-17, IL-10, MCP-1, MIP-1A, IP10, and TNF-α being observed to be higher in COVID-19 patients undergoing treatment in intensive care units than in any other category of COVID-19 patients." (PMID 32984253, 2020). "Thus, therapies targeting IL-6, IL-10, and TGF-β could be investigated as means of improving NK cell antiviral immunity in cases of COVID-19." (PMID 32973527, 2020). "Further, interleukin 10 (IL-10), interleukin 6 (IL-6), interleukin 1 (IL-1), interleukin 2R (IL-2R), and tumor necrosis factor alpha (TNF-α) levels might exceed the upper limit in COVID-19 patients." (PMID 32516940, 2020). "Furthermore, unlike SARS patients, patients with COVID-19 also have elevated levels of Th2 cell-secreted cytokines (such as IL-4 and IL-10), which inhibit the inflammatory Th1 responses." (PMID 33324414, 2020). "In our study, we also found that, compared to mild cases, the serum levels of IL-10, TNF-α and IL-6 were significantly higher in the severe cases, indicating that severe cases are prone to form an inflammatory storm, leading to rapid deterioration of COVID-19 eventually." (PMID 33154753, 2020). "Consequently, the administration of BDs of the mRNA COVID-19 vaccine was found to be safe, although transient alteration of systemic inflammation status is expected as a result of T cell priming (IL2-R, IL-6, TNF-α), followed by the deactivation (IL-10) of pro-inflammatory cytokine synthesis." (PMID 40266144, 2025). "The analyses showed that COVID-19 patients with cardiovascular co-morbidities who also consumed statins had significantly lower plasma levels of IL-6 (adjusted p = 0.027), TNFα (adjusted p = 0.036), and IL-10 (adjusted p = 0.025) compared to COVID-19 patients with no CVD co-morbidities." (PMID 39518552, 2024).
COVID-19 (continued). "We also observed an increase in immunoregulatory IL-10, which could serve as a negative feedback signal to restrict hyper-inflammation, or, as recently proposed, contribute to inflammatory pathogenesis and severity of COVID-19." (PMID 37174682, 2023). "Finally, since MAFB-dependent factors like IL-10, SPP1, CCL2, and CXCL13 are biomarkers for COVID-19 severity, we next assessed whether additional MAFB-dependent soluble factors might also predict COVID-19 severity or outcome." (PMID 37917179, 2023). "Interestingly, IL-6 and IL-10 are increased among severe and non-survivor COVID-19 cases." (PMID 35572964, 2022). "This suggests that in critical COVID-19, strong elevation of IL-6 (e.g., > 100-120 pg/mL) and CRP levels (e.g., > 160-200 mg/L) could reflect augmented IL-6 cis-signalling in the attempt to exert homeostatic roles, while IL-10 further strengthens the predominance of SOCS3 over STAT3 signal." (PMID 35340805, 2022). "Since this phenomenon appears to be unique to COVID-19, as opposed to other highly pathogenic hCoV infections, it stands to reason that SARS-CoV-2 could induce an early and sustained induction of IL-10 by some mechanism or pathway that neither SARS-CoV nor MERS-CoV is able to." (PMID 34452323, 2021). "However, although certain studies have shown that plasma IL-6 and IL-10 could be used as factors to predict the progression of COVID-19, in our cohort, their values could not be used in isolation to distinguish between patient groups." (PMID 34960790, 2021). "As for CXCL10, it can be advocated that an initial more robust TH1 response with monocytes/macrophage over activation in COVID-19 patients, as compared to non-COVID-19 patients, could lead to a subsequent IL-10 overproduction in order to limit T cell responses." (PMID 33272291, 2020). "Second, certain pro-inflammatory cytokines (IL2, IL7, IL10, GCSF, IP10, MCP1, MIP1A, and TNF) were further increased in ICU patients compared with non-ICU patients, indicating that excessive acute inflammatory responses may lead to septic shock and death in COVID-19 patients." (PMID 32442210, 2020). "Indeed, defined circulating factors - CXCL8, IL-10, IL-15, IL-27, and TNF-α - positively correlate with older age, longer hospitalization, and a more severe form of the disease and may thus represent the leading signature in critical COVID-19 patients." (PMID 33159040, 2020). "Furthermore, serum concentrations of IL-10, IL-6, and TNF-α were significantly lower in patients in the disease resolution in comparison to the disease period, whereas the total number of T cells, CD4+ T cells, and CD8+ T cells was restored during the decline period of COVID-19." (PMID 32916812, 2020). "measured plasma cytokines in patients with COVID-19 and found that ICU patients exhibited markedly elevated levels of IL-10 in their plasma when contrasted with those in non-ICU settings." (PMID 41601653, 2026). "In contrast, COVID-19 negative individuals showed lower-magnitude responses for TNF, IL-10, and IL-17A but exhibited multiple peaks in IL-2, IL-6, and IFN-γ production." (PMID 40406109, 2025). "Specifically, we compared the levels of IFN-γ, IL-6, IL-22, IL-4, IL-8, IL-10, and IL-17A between anti-SARS-CoV-2 IgG-positive and seronegative individuals, all without a history of COVID-19." (PMID 40160814, 2025). "Upon comparison of the biomarker levels with those in control cases, it was detected that critically ill COVID-19 controls without AKI had lower levels of uSerpinA3, uKIM-1, uNGAL, TNF-α, and IL-10." (PMID 40804924, 2025). "Similar to IL-6, IL-10, and TNF- α, CCL-3 and CXCL-13 levels were not significantly different between mild-to-moderate COVID-19 patients, recovered individuals, and healthy controls." (PMID 38646483, 2024).
COVID-19 (continued). "Statistical analysis revealed that levels of cytokines IL-6, IL-8, IL-10, sCD25, and chemokines IP-10, and MIG in the peripheral blood of severe COVID-19 patients were significantly higher than those in non-severe patients (P < 0.05)." (PMID 39654886, 2024). "In univariable analyses, individuals with PASC tended to have lower levels of sCD14, IL10, IL17, IL1β, IL6 and TNFα compared to participants without PASC at 9–12 weeks after COVID-19 onset." (PMID 39008486, 2024). "A study in Russia among 376 HIV/COVID-19 patients (171 without ART and 205 with ART) suggested that elevated anti-inflammatory markers such as IL-10 and TGFβ, reduced CD4+/CD8+ cell ratios led to an increase in exhausted T cells in ART naïve patients." (PMID 38628843, 2024). "This study found that the levels of cytokines IL-6, IL-8, IL-10, sCD25, and chemokines IP-10, and MIG in the peripheral blood of severe COVID-19 patients were significantly higher than those in non-severe patients (P < 0.05)." (PMID 39654886, 2024). "We determined that increased interleukin (IL)-6 and IL-10, and tumor necrosis factor-α and interferon gamma were not predictive of severe ANE and mortality in children with COVID-19 in this study." (PMID 37602239, 2023). "Monocytes of HD + COVID-19 patients secreted significant higher levels of the pro-inflammatory cytokines GM-CSF, IL-1β, IL8, IL-10, CCL2 and CCL3 compared to non-infected HD patients." (PMID 36675231, 2023). "Remarkably, COVID-19 patients requiring intensive care unit (ICU) admission presented higher levels of CCL2, CXCL10, IL-2, IL-7, IL-10 and TNF-α than non-ICU patients, hinting the linkage between the cytokine storm and COVID-19 deterioration." (PMID 37251383, 2023). "Non-severe COVID-19 cases showed an increase in IL1β, IL-6, IL-10 and TNF and severely ill patients had higher levels of the cytokines IL-6, IL-10 and CXCL8." (PMID 37515295, 2023). "Furthermore, researchers showed that the patients with COVID-19 had extremely high concentrations of serum IL-10 after SARS-CoV-2 infection, together with increased concentrations of exhaustion markers like PD-1 and Tim-3 on the T cells, implying that IL-10 may be the mechanism of action." (PMID 36679947, 2023). "More than 98% of the HCWs with severe COVID-19 had cytokine levels (IFN-γ, IL-10, IL-2 and IL-4) in the normal ranges." (PMID 36908474, 2023). "A positive correlation of METRNβ with IL10, IL6, and CCL7 was observed among the COVID-19 patients, while a negative correlation was observed with sCD40L." (PMID 36798115, 2023). "In a similar way, the COVID-19 group with SIgA presented higher levels of IL-10 and IFN-γ than the values found in the COVID-19 group without SIgA." (PMID 35686128, 2022). "We also tested the levels of IL-10 and EGF mRNAs in PBMCs of COVID-19 patients and controls, but none significant differences were observed." (PMID 36414650, 2022). "Here, we investigated ex-vivo the effect of IL-10 on the SARS-CoV-2-specific and -unspecific response of COVID-19 patients (with or without vaccination) and in vaccinated controls, using a whole-blood platform." (PMID 36148228, 2022). "Using a previous model, the cytokine micro-environments found in mild, moderate, and severe COVID-19 with and without TGF-β and IL-10 was we simulated." (PMID 36678366, 2022). "Significant levels of the inflammatory cytokines IL-6, IL-8, IL-10, and TNF-α have been documented in severe COVID-19 compared with non-severe disease cases, reflecting this phenomenon." (PMID 36556051, 2022). "An exception was a negative correlation between MMP-9/BDNF with IL-10/IL-17 in moderately ill and a highly positive correlation of this ratio with MMP-8 in mild, moderate, and critically COVID-19 groups." (PMID 36438922, 2022). "While the levels of IP-10, IL-15 and IL-18 were exclusively increased in SOTRs with COVID-19, Non-SOT patients with COVID-19 showed solely higher levels of IFN-β, IL-2, IL-10, GM-CSF and low levels of Eotaxin, MCP-1, MIP-1β, IL-4, IL-5." (PMID 35075453, 2022).